EEF2K (eukaryotic elongation factor 2 kinase)
Diseases named in the same sentence as EEF2K in open-access papers (continued):
Sharing a sentence is not in itself a finding about the gene and the disease.
gastric cancer (3 papers, 2019 to 2024). A primary or metastatic malignant neoplasm involving the stomach. "In contrast, in other diseases of ovarian cancer and gastric cancer, eEF2K mutation status was not significantly correlated with the clinical prognosis of OS, PFS, RFS, and DSS." (PMID 39592671, 2024). "Moreover, the decreased levels of protein kinase A (PKA), phosphorylated AMP-activated protein kinase (pAMPK), and eukaryotic elongation factor 2 kinase (eEF2k) after β-cryptoxanthin treatment led to the inactivation of AMPK signaling in the same gastric cancer cells." (PMID 32859058, 2020). "Recent studies are consistent with our findings that eEF2K is highly expressed in a variety of solid tumors, including breast, pancreatic, lung, and hepatocellular carcinomas, and may play a tumor-suppressive role in colorectal, endometrial, and gastric cancer tissues." (PMID 39592671, 2024).
ovarian carcinoma (3 papers, 2021 to 2025). A malignant neoplasm originating from the surface ovarian epithelium. "It was also reported that eEF2K promotes the proliferation of ovarian cancer cells and that its expression is positively correlated with poor prognosis." (PMID 33673713, 2021). "Additionally, eEF2K has been reported to enhance the proliferation of ovarian cancer cells, with its elevated expression correlating with poor clinical outcomes." (PMID 39592671, 2024).
brain cancer (2 papers, 2013 to 2014). A primary or metastatic malignant neoplasm affecting the brain.
chronic lymphocytic leukemia (2 papers, 2024 to 2025). "In chronic lymphocytic leukemia (CLL), targeting the eEF2/eEF2K axis through phosphorylation effectively suppresses disease progression by modulating proteins critical for cell proliferation." (PMID 39707196, 2024).
leukaemia (2 papers, 2022 to 2023). "Based on the US FDA‐approved drug library, we have further identified cytarabine, a drug used in the treatment of several types of leukaemia, which could decrease EEF2K expression significantly." (PMID 35184394, 2022).
neuroblastoma (2 papers, 2017 to 2018). Neuroblastoma (NB) is the most common solid, extracranial childhood tumor. "Depletion of eEF2K (by siRNA) impairs MYCN-amplified neuroblastoma xenograft growth under conditions of caloric restriction." (PMID 29186827, 2017). "To study the effects of eEF2K inhibition on AS toxicity, we employed differentiated mouse neuroblastoma N2A cells overexpressing either wild-type AS (ASyn-WT) or the A53T mutant (ASyn-A53T) +/− siRNA mediated eEF2K knockdown (kd), and measured cytotoxicity in these cells." (PMID 29961428, 2018). "In neuroblastoma cells in which the oncogene MYCN is amplified, eEF2K is also activated and is required for these cells to survive nutrient withdrawal, as shown by the observation that they are very sensitive to the eEF2K inhibitor A-484954." (PMID 29186827, 2017).
stomach adenocarcinoma (2 papers, 2022 to 2025). "EEF2K is also a clinical indicator of metastasis and prognosis of stomach adenocarcinoma and could serve as a potential therapeutic target." (PMID 36601599, 2022).
acute myeloid leukemia (1 paper, 2022). Acute myeloid leukemia (AML) is a group of neoplasms arising from precursor cells committed to the myeloid cell-line differentiation. "Systematic analysis in 12 acute myeloid leukemia cell lines revealed that eEF2K activity was increased in cells for which PI3K plus MEKi cotreatment is synergistic, while PKC potentially mediated resistance to such cotreatment." (PMID 35513296, 2022).
Arthritis (1 paper, 2023). Inflammation of a joint. "The eEF2K KO mice with CIA also showed a higher arthritis score." (PMID 37875468, 2023). "We surmised that absence of eEF2K showed higher inflammation and more severe arthritis development." (PMID 37875468, 2023). "These experiments collectively showcased that the lack of eEF2K resulted in an inflammatory microenvironment, exacerbated inflammation-related diseases, promoted colitis, multiple sclerosis, and arthritis through dysfunctional CD4+ T cells, and increased the secretion of pro-inflammatory cytokines." (PMID 37875468, 2023). "Furthermore, while our study primarily focused on the effects of eEF2K on CD4+ T cells and arthritis, it’s important to consider that other immune cell types may potentially impact the severity of arthritis as well." (PMID 37875468, 2023).
brain tumor (1 paper, 2014). "Recently, eEF2K was shown to maintain survival of brain tumor cells undernutrient deprivation." (PMID 25330770, 2014).
breast tumors (1 paper, 2012). "The purpose of this study was to evaluate the potential of targeting the protein kinase eEF-2K in breast tumors, with the objectives of determining whether targeting eEF-2K 1) impedes tumor growth, and 2) sensitizes tumors to chemotherapy." (PMID 22911754, 2012).
colitis (1 paper, 2023). Inflammation of the colon. "Flow cytometry analysis demonstrated that, after the development of colitis, the eEF2K knockout group had higher populations of IL-17A+ CD4+ T cells in the colons compared to the WT group." (PMID 37875468, 2023). "Strikingly, the use of C188-9, a small molecule targeting STAT3, mitigates colitis in a murine immunodeficiency model receiving eEF2K knockout (KO) CD4+ T cells." (PMID 37875468, 2023). "The increase in STAT3 expression in eEF2K knockout CD4+ T cells prompted us to explore the role of this transcription factor in the eEF2K-mediated regulation of colitis." (PMID 37875468, 2023). "NSG mice receiving eEF2K KO CD4+ T cells (eEF2K KO group) underwent significant weight losses, as compared to the WT group, and colitis was more severe in the eEF2K KO group than in controls, as evidenced by their shortened colons." (PMID 37875468, 2023). "Remarkably, while C188-9 treatment significantly alleviated the severity of colitis in the eEF2K KO group, this STAT3 inhibitor did not affect the severity of the disease in the WT group, as determined by body weight, colon size, and pathologic score." (PMID 37875468, 2023).
colon adenocarcinoma (1 paper, 2021). "Similar results are seen for the protein expression of RPL24, eEF2K, and eEF2 from colon adenocarcinoma samples, and for the three mRNAs in rectal adenocarcinoma." (PMID 34895463, 2021). "(B) RNA expression levels of RPL24, EEF2K, and EEF2 between normal colon and colon adenocarcinoma samples using data extracted from The Cancer Genome Atlas by TNMplot." (PMID 34895463, 2021).
diabetes (1 paper, 2013). "In the diabetic sternohyoid, three of the five calcium channel genes with decreased expression (Fstl1, Atp2b3, Eef2k, Gpd2, Myl6b) were decreased in previous diabetes studies." (PMID 24199937, 2013). "Several eukaryotic translation initiation and elongation factors are decreased in streptozotocin-induced diabetic rodent gastrocnemius muscle, however until the present study eukaryotic elongation factor kinase (Eef2k) has not previously been significantly changed due to diabetes." (PMID 24199937, 2013).
Dravet syndrome (1 paper, 2022). "Even though future studies focused on clarifying the activity of eEF2K inhibition on Dravet syndrome comorbidity are necessary, our data suggest eEF2K pharmacological inhibition as an innovative therapy for Dravet syndrome." (PMID 34980259, 2022). "This work provides strong evidence that genetic deletion of eEF2K in the Scn1a ± mice, a mouse model of Dravet syndrome, can rescue both epileptic phenotype and behavioral alterations." (PMID 34980259, 2022). "To elucidate the role of eEF2K pathway in the etiopathology of Dravet syndrome we generated a new mouse model deleting the eEF2K gene in Scn1a ± mice." (PMID 34980259, 2022). "We demonstrated that the genetic deletion of eEF2K in the Scn1a ± mice rescued the main phenotypes such as epileptic seizure and deficit in behavior, which characterized the Dravet syndrome suggesting eEF2K as a possible pharmacological target." (PMID 34980259, 2022). "Thus, we investigated the effect of inhibition of eEF2K on the epileptic and behavioral phenotype of Scn1a ± mice, a murine model of Dravet Syndrome." (PMID 34980259, 2022). "Notably, pharmacological inhibition of eEF2K in adult mice was also sufficient to normalize the EEG profile of Scn1a ± mice proposing eEF2K as a new pharmacological target not only for Dravet syndrome but also for several neuronal diseases in which eEF2K activity is altered." (PMID 34980259, 2022). "Additionally, we show that pharmacological inhibition of eEF2K ameliorated the altered EEG phenotype, demonstrating that treatments aimed to decrease eEF2K activity might represent a new approach for treating patients that are affected by Dravet syndrome." (PMID 34980259, 2022).
endometrial cancer (1 paper, 2024). Primary or metastatic malignant neoplasm involving the endometrium (mucous membrane that lines the endometrial cavity). "Notably, the eEF2K phosphorylation site S474 reported in our study was highly expressed in endometrial cancer, so it can be assumed that different phosphorylation sites perform different functions." (PMID 39592671, 2024).
Intellectual disability (1 paper, 2014). "We also identified three 16p12.1(hg 18) microdeletions involving the EEF2K and CDR2 genes, which have been previously linked to intellectual disability and neuropsychiatric phenotypes." (PMID 25516202, 2014).
intestinal cancer (1 paper, 2020). "The pharmacological targeting of mTORC1 required functional eEF2K, suggesting that mTORC1 promotes intestinal cancer by repressing eEF2K." (PMID 32298235, 2020).
intestinal tumors (1 paper, 2020). "In contrast to the findings that support the tumor-promoting role of eEF2K, two studies showed that eEF2K impedes the initiation and growth of intestinal tumors, suggesting that the role of eEF2K in cancer is more complex than simply exerting a cytoprotective effect." (PMID 32054489, 2020).
intracranial hemorrhage (1 paper, 2017). Bleeding within the SKULL, including hemorrhages in the brain and the three membranes of MENINGES. "Furthermore, EC-specific overexpression of Eef2k (“Flk1:tdT-P2A-Eef2k”) also caused intracranial hemorrhage (P < 0.01), DAPI leakage (P < 0.001), and reduction of Cdh5 expression (P < 0.01)." (PMID 28429770, 2017). "Moreover, knockdown of eef2k alleviated the intracranial hemorrhage (P < 0.01), DAPI leakage (P < 0.05) and reduction of Cdh5 expression (P < 0.05) in miR-132 morphants." (PMID 28429770, 2017). "On the other hand, treatment with the eEF2K non-specific activator rapamycin (2 μM) led to intracranial hemorrhage in wildtype larvae (P < 0.05) and further aggravated the hemorrhagic defect of miR-132 morphants (P < 0.001)." (PMID 28429770, 2017).
invasive breast carcinoma (1 paper, 2024). A carcinoma that infiltrates the breast parenchyma. "Interestingly, based on data from the TCGA database, we found that eEF2K gene expression and protein expression in invasive breast carcinoma were contradictory." (PMID 39592671, 2024).
lung adenocarcinoma (1 paper, 2024). A carcinoma that arises from the lung and is characterized by the presence of malignant glandular epithelial cells. "The same observation has been achieved in lung adenocarcinoma (LUAD) where eEF2K is typically overexpressed to promotes the migration, invasion, and angiogenesis of LUAD cells, thereby driving tumor progression." (PMID 39592671, 2024).
lung fibrosis (1 paper, 2018). "Two independent reports demonstrate a role for miR-877 as a tumor suppressor in renal cell carcinoma by targeting eukaryotic elongation factor-2 kinase (eEF2K), and in myofibroblast differentiation and bleomycin-induced lung fibrosis by targeting targets Smad7." (PMID 30029522, 2018).
multiple sclerosis (1 paper, 2023). A progressive autoimmune disorder affecting the central nervous system resulting in demyelination. "Taken together, the data indicate that the deficiency of eEF2K promotes Th17 cell responses in inflammation-related diseases, including rheumatoid arthritis and multiple sclerosis." (PMID 37875468, 2023). "Crucially, the deficiency of eEF2K exacerbates the severity of inflammation-related diseases, including rheumatoid arthritis, multiple sclerosis, and ulcerative colitis." (PMID 37875468, 2023). "Furthermore, we have documented that the absence of eEF2K worsens the occurrence of ulcerative colitis, multiple sclerosis, and the onset of rheumatoid arthritis in murine models, primarily by amplifying the production of pro-inflammatory cytokines." (PMID 37875468, 2023). "Boosting eEF2K levels in CD4+ T cells to curtail the proinflammatory microenvironment could potentially usher in a novel approach for the prevention and treatment of inflammatory conditions, such as rheumatoid arthritis, multiple sclerosis, and ulcerative colitis." (PMID 37875468, 2023).
rheumatoid arthritis (1 paper, 2023). A chronic, systemic autoimmune disorder characterized by inflammation in the synovial membranes and articular surfaces. "This suggests that the dysregulation of eEF2K and its impact on CD4+ T cell function, including the promotion of Th17 profiles, may contribute to the pathogenesis of diseases like rheumatoid arthritis." (PMID 37875468, 2023).
synucleinopathies (1 paper, 2018). "By using multiple experimental approaches, we elucidate the relevance of eEF2K in AS toxicity, and discuss the potential utility of eEF2K inhibition in PD and related synucleinopathies." (PMID 29961428, 2018).
systemic lupus erythematosus (1 paper, 2021). An autoimmune multi-organ disease typically associated with vasculopathy and autoantibody production. "Further involvement of eEF2K in autoimmune disorders was revealed in a study that detected anti-eEF2K antibodies from sera of systemic lupus erythematosus patients." (PMID 34532346, 2021).
viral infection (1 paper, 2024). "To assess the role of eEF-2K in CD8+ T cell responses to viral infection, we infected WT and eEF-2K−/− mice with 2 million PFU of VACV, and then analyzed CD8+ B8R+ T cells for over 35 days." (PMID 39861816, 2024). "Despite these findings, the precise mechanisms by which eEF-2K regulates T cell responses during viral infections remain poorly understood." (PMID 39861816, 2024). "RNA sequencing showed that eEF-2K−/− VACV-specific effector CD8+ T cells had enhanced functionality, rendering them more effective during the effector phase of viral infection." (PMID 39861816, 2024). "TRAF3 expression was significantly elevated at both mRNA and protein levels in VACV-specific eEF-2K−/− effector CD8+ T cells, which is consistent with its known role in promoting type I interferon responses during viral infections." (PMID 39861816, 2024). "RNA sequencing demonstrated that eEF-2K−/− VACV-specific effector CD8+ T cells had enhanced functionality, which improves their capacity to combat viral infection during the effector phase." (PMID 39861816, 2024).
tumor (76 papers, 2010 to 2026). "Studies indicate that eEF2K is associated with key oncogenic processes, such as tumor proliferation, survival, tumorigenesis, invasion and drug resistance." (PMID 39592671, 2024). "A pan-cancer analysis of eEF2K expression, genetic variants, and clinical relevance across multiple tumor types was performed using data from the Cancer Genome Atlas (TCGA) and GEO." (PMID 39592671, 2024). "The close association between EEF2K and tumour progression highlighted EEF2K as an attractive target for cancer therapy." (PMID 35184394, 2022). "Recent research has shown that eEF2K is associated with tumor survival, proliferation, migration, and invasion." (PMID 34532346, 2021). "Reducing P-eEF2 by inactivating its inhibitory kinase, eEF2K, completely restores translation elongation and protein synthesis rates as well as reversing the beneficial effect of Rpl24Bst mutation in our tumour models." (PMID 34895463, 2021). "Previous studies have found that eEF2K is associated with tumor proliferation and survival, tumorigenesis, invasion, drug resistance, and poor prognosis." (PMID 33673713, 2021). "Heterozygous inactivation of Eef2k resulted in a slight reversal of the extension of survival associated with Rpl24Bst mutation in the Apcfl/+ KrasG12D/+ tumour model." (PMID 34895463, 2021). "When tumor cells are exposed to nutrient deprivation or therapeutic stress, eEF-2K plays an important role in promoting tumor survival and causing chemotherapy resistance by activating autophagy." (PMID 33144562, 2020). "The key goal now is to discover which tumour types, or indeed subtypes, are susceptible to what mode of eEF2K targeting." (PMID 32298235, 2020). "This distinctive synthetic lethality circuit created by APC inactivation in CRC strongly supports the intestine-specific tumor-suppressive effect of EEF2K and its association with better prognosis in CRC patients." (PMID 31266475, 2019). "Our findings suggest that miR-603 functions as a tumor suppressor and loss of miR-603 expression leads to increase in eEF2K expression and contributes to the growth, invasion, and progression of TNBC." (PMID 28036267, 2017). "It remains to be clarified why this effect is observed for Apc-deficient colorectal cancer, whereas eEF2K promotes tumour growth in other settings." (PMID 29186827, 2017). "Mutations occur in the eEF2K genes in the cancer tumor samples." (PMID 39592671, 2024). "Importantly, eEF2K was also found to enhance the expression of PD-L1, and is thus implicated for its role in blocking tumor immunosurveillance." (PMID 35294699, 2022). "In addition, elevations of HSP90 and the phospho-Akt proteins have been reported in other types of cells deficient in eEF-2K, including the intestinal stem cells, epithelial cells, human tumor cells, and mouse embryonic fibroblasts." (PMID 35108044, 2022). "Numerous studies have demonstrated that EEF2K is involved in various tumour‐associated processes, including cell cycle, apoptosis, angiogenesis, epithelial–mesenchymal transition and sensitivity to chemotherapies in tumour progression." (PMID 35184394, 2022). "Therefore, our studies revealed molecular mechanisms underlying tumor PD-L1 regulation and uncovered an inhibitory role of eEF2K in antitumor immunity." (PMID 35347072, 2022). "eEF2K expression has been shown to protect cancer cells from hypoxia by producing the expression of specific proteins, such as microtubule-associated proteins, resulting in the expression of tumor-promoting proteins and growth factors." (PMID 35010954, 2021). "Furthermore, inactivation of eEF2K reverted the survival benefit of the Rpl24Bst mutation in the Apcfl/+ KrasG12D/+ tumour model." (PMID 34895463, 2021).